PNKP (polynucleotide kinase 3'-phosphatase)
Diseases named in the same sentence as PNKP in open-access papers (continued):
Sharing a sentence is not in itself a finding about the gene and the disease.
glioma (4 papers, 2021 to 2024). A benign or malignant brain and spinal cord tumor that arises from glial cells (astrocytes, oligodendrocytes, ependymal cells). "They suggested that polynucleotide kinase 3′-phosphatase (PNKP) is a critical mediator of this aberrant repair process, showing increased association with mutant H3.3; hence, targeting PNKP is a promising therapeutic strategy for gliomas and other cancers with these mutations." (PMID 39439908, 2024). "This newly discovered role of PNKP is an autonomous oncogenic mechanism that contributes to genome instability and stimulates tumor cell growth in pediatric high-grade gliomas (pHGG)." (PMID 39395804, 2024).
brain tumor (3 papers, 2022 to 2025). "Studies have associated the loss of PNKP enzyme activity with immunodeficiency and tumor susceptibility, including high-grade brain tumors associated with PNKP gene mutations." (PMID 39833032, 2025). "Here, we characterized the biochemical significance of 2 germ-line point mutations in the PNKP gene of a 3-year old male with MSCZ who presented with a high-grade brain tumor (glioblastoma multiforme) within the cerebellum." (PMID 35354845, 2022). "Although not definitive, these cases of relatively rare brain tumors in AOA4 and MCSZ strongly suggest a link between PNKP mutation and elevated cancer risk." (PMID 35354845, 2022). "These collective findings provide compelling evidence for the critical involvement of PNKP in DNA replication (reported here) and in pHGG pathogenesis and offer potential avenues for targeted therapeutic interventions against this aggressive pediatric brain tumor." (PMID 39395804, 2024).
Epileptic encephalopathy (3 papers, 2014 to 2025). A condition in which epileptiform abnormalities are believed to contribute to the progressive disturbance in cerebral function. "There are two genes on the fringe of both clusters, PNKP and SPTAN1, showing weak co-expression with the majority of Epileptic Encephalopathy genes." (PMID 25014031, 2014).
Immunodeficiency (3 papers, 2015 to 2025). Failure of the immune system to protect the body adequately from infection, due to the absence or insufficiency of some component process or substance. "Interestingly, neither patient developed tumors, even in adulthood, supporting previous observations that PNKP dysfunction does not generally increase the risk of malignancy or immunodeficiency, despite its role in DNA repair." (PMID 41283299, 2025).
neuroblastoma (3 papers, 2015 to 2019). Neuroblastoma (NB) is the most common solid, extracranial childhood tumor. "(A) Nuclear extract (NE), and cytosolic extract (CE) were purified from human neuroblastoma SH-SY5Y cells and the protein fractions were analyzed by western blots (WBs) to detect HTT, ATXN3, PNKP, and HAP1 levels in these sub-cellular fractions." (PMID 30994454, 2019).
prostate carcinoma (3 papers, 2018 to 2025). A carcinoma that arises from epithelial cells of the prostate gland. "Targeting of PNKP was previously proposed to have a therapeutic potential in several human cancers, including lung, breast, colorectal, and prostate cancer, particularly in combination with γ-radiation or topoisomerase I inhibitor." (PMID 40743845, 2025). "In prostate cancer cells, combination of PNKP inhibitor (A12B4C3) and carbon ion irradiation induced cell cycle arrest and apoptotic death." (PMID 40743845, 2025). "It is expected that inhibition of PNKP activity may enhance the efficacy of the charged particle irradiation in the radioresistant prostate cancer cell line PC-3." (PMID 29320576, 2018). "Present findngs led us to conclude that, PNKP inhibition through A12B4C3 may be a suitable alternative to enhance cell death in radioresistant prostate cancer cell line like PC-3 on the exposure to carbon ion radiation." (PMID 29320576, 2018). "Our findings suggest that combined treatment of carbon ion irradiation and PNKP inhibition could enhance cellular radiosensitivity in a radioresistant prostate cancer cell line PC-3." (PMID 29320576, 2018). "Hence the present study is targeting PNKP inhibition in combination with C-ion radiation to enhance the cell killing in radioresistant prostate cancer cell line PC-3.PNKP inhibition may be a promising approach to enhance clinical outcome of C-ion radiation in radioresistant cancer cells." (PMID 29320576, 2018).
Spinocerebellar ataxia type 3 (3 papers, 2015 to 2024). "Alterations in PNKP expression levels in humans have also been linked to the pathogenesis of spinocerebellar ataxia type 3 (SCA3) in combination with mutant Ataxin-3 (ATXN3)." (PMID 34226276, 2021). "We have made the unexpected observation that PNKP stably associates with Ataxin-3 (ATXN3), a polyglutamine repeat-containing protein mutated in spinocerebellar ataxia type 3 (SCA3), also known as Machado-Joseph Disease (MJD)." (PMID 25633985, 2015).
glioblastoma (2 papers, 2020 to 2022). The most malignant astrocytic tumor (WHO grade IV). "Finally, GSK3B, PNKP and RB1, which were suggested as targets to control the neuroinflammation in response to WNV infection in the glioblastoma cell line U251, were not modulated in our study." (PMID 32374750, 2020).
Huntington disease (2 papers, 2022 to 2024). Huntington disease (HD) is a rare neurodegenerative disorder of the central nervous system characterized by unwanted choreatic movements, behavioral and psychiatric disturbances and dementia. "SUMO E3 ligase PIAS1 has been found to modulate the activity of polynucleotide kinase-phosphatase (PNKP), a damaged DNA-end processing enzyme, in response to the transcription-coupled DSB repair in genes associated with Huntington’s disease (HD) pathology." (PMID 35563044, 2022). "In our previous study, we also demonstrated that PNKP activity, not its protein level, is severely abrogated in Huntington's disease (HD), a major polyglutamine disease, resulting accumulation of DSBs." (PMID 38224455, 2024).
lung carcinoma (2 papers, 2016 to 2022). "On the other hand it was demonstrated that small inhibitors of PNKP increased the response to radiations of human lung carcinoma cells." (PMID 26754536, 2016).
neuropathy (2 papers, 2018 to 2022). A disorder affecting the nervous system that manifests with pain, tingling, numbness, and/or muscle weakness. "Therefore, this study confirms the role of PNKP mutations in peripheral polyneuropathies and add data associated to the variability of the PNKP-related phenotype, due to the late age of onset of the neuropathy in our PNPK mutated patients." (PMID 30039206, 2018). "More recently, new causal-genes were identified in undiagnosed families, including PNKP in eight families with AOA4, MAG in one family with AOA and neuropathy, and DAB1 in three AD families with SCA37." (PMID 35326432, 2022). "Both PNKP and SETX were universally associated with neuropathy, but not with AOA; the reason why AR4 had not been previously tested for SETX." (PMID 35326432, 2022).
Primary microcephaly (2 papers, 2013 to 2022). Head circumference below 2 standard deviations below the mean for age and gender at birth. "Haplotype analysis using microsatellite markers around the MCPH1-7 and PNKP loci in an Italian family with two sons with primary microcephaly, revealed possible linkage to the MCPH3 locus." (PMID 23587236, 2013).
axonal peripheral neuropathy (1 paper, 2018). "In conclusion, we provide evidence that PNKP is the main gene related to CMT2B2 instead of MED25, and that it should be considered as a gene involved in an axonal peripheral neuropathy with late age onset, cerebellar atrophy, and with or without oculomotor apraxia." (PMID 30039206, 2018).
hepatocellular carcinoma (1 paper, 2017). A malignant tumor that arises from hepatocytes. "For example, CTBP1 is listed by Cancer Resource, and TASP1 is also a drug target, which is used to combat novel diseases whose candidate genes are targeted by HNF4alpha splice variants in hepatocellular carcinomas, as well as PNKP and RAG2." (PMID 28691014, 2017).
lung adenocarcinoma (1 paper, 2014). A carcinoma that arises from the lung and is characterized by the presence of malignant glandular epithelial cells. "The importance of PNKP in the cellular DNA damage response has been demonstrated by the observation that an shRNA knockdown of PNKP caused an elevation in the sensitivity of A549 human lung adenocarcinoma cells to oxidative stress induced by hydrogen peroxide and ionizing radiation." (PMID 25076968, 2014).
myeloid leukemia (1 paper, 2021). A clonal proliferation of myeloid cells and their precursors in the bone marrow, peripheral blood, and spleen. "The Reilly group showed that A12B4C3 sensitizes human myeloid leukemia cells to radio-immunotherapy providing more evidence for the promise of PNKP inhibitors as radio-sensitizers." (PMID 35004293, 2021).
primary biliary cirrhosis (1 paper, 2021). "However, our analysis associated rs11546996 to PNKP (P-value = 1.05e-6, FDR = 0.026) thereby potentially identifying a new causal gene for primary biliary cirrhosis by accounting for methylation in eQTL mapping." (PMID 33691021, 2021).
Telangiectasia (1 paper, 2021). Telangiectasias refer to small dilated blood vessels located near the surface of the skin or mucous membranes, measuring between 0.5 and 1 millimeter in diameter. "However, patients with AOA2/4 do not exhibit telangiectasia, and our patients did neither carry putatively causative SETX nor PNKP variants." (PMID 33779842, 2021).
triple-negative breast carcinoma (1 paper, 2025). An invasive breast carcinoma which is negative for expression of estrogen receptor (ER), progesterone receptor (PR), and human epidermal growth factor receptor 2 (HER2). "Here we show that PNKP is highly expressed in triple negative breast cancer (TNBC) and associated with poor prognosis and chemoresistance." (PMID 40743845, 2025).
uveal melanoma (1 paper, 2023). A melanoma derived from melanocytes of the uveal tract. "We previously observed intron retention in POLD1 (exon 22–23), PNKP (exon 19–20), ATM, and ATR in uveal melanoma cell lines treated with PRT543 with concomitant loss in protein expression." (PMID 37861290, 2023).
ZIKV infection (1 paper, 2022). "We propose that the functional PNKP deficiency and dysregulation of CycA/CDK1 mitotic activity during ZIKV infection of neural progenitors result in MC, contributing to the molecular mechanism underlying neurodevelopmental pathologies of congenital ZIKV infections." (PMID 35412344, 2022). "Here, we show that ZIKV infection caused the activation of cytoplasmic CycA/CDK1 and unscheduled mitotic entry in the presence of DNA breaks, which accumulated in infected cells due to the cytoplasmic localization of PNKP, leading to grossly abnormal mitoses culminating in MC." (PMID 35412344, 2022). "PNKP relocalizes to the cytoplasm, where it colocalizes with NS1 during ZIKV infection." (PMID 35412344, 2022). "As ZIKV infection did not affect total PNKP levels, PNKP relocalizes to these cytoplasmic clusters from the nucleus, and possibly mitochondria." (PMID 35412344, 2022).
cancer (15 papers, 2015 to 2025). A tumor composed of atypical neoplastic, often pleomorphic cells that invade other tissues. "Through RNAi screening, we made the exciting discovery that the deficiency of a tumor suppressor protein, i.e., phosphatase and TENsin homolog (PTEN), makes cancer cells even more sensitive to the PNKP inhibition." (PMID 35004293, 2021). "Human polynucleotide kinase-phosphatase (PNKP) is identified as a key enzyme involved in DNA repair following damage by IR or topoisomerase I inhibitors (e.g. irinotecan) in many types of cancer including CRC." (PMID 35004293, 2021). "PNKP has been identified as a potential therapeutic target in different types of cancer, as depletion of PNKP in cancer cells or tumor xenografts has shown a synthetic lethal partnership with the loss of the tumor suppressor protein PTEN." (PMID 35004293, 2021). "Inhibition of the DNA repair enzyme polynucleotide kinase/phosphatase (PNKP) increases the sensitivity of cancer cells to DNA damage by ionizing radiation (IR)." (PMID 35004293, 2021). "Since the inhibiting PNKP activity is an important target for anticancer drugs, in addition to the inhibition of phosphatase and kinase enzymatic activity, inhibiting phosphorylation at T118 of PNKP might be a potent target for cancer therapy." (PMID 40146629, 2025). "Furthermore, a recent report identified an MCSZ patient with GBM that was reported to have two somatic PNKP point mutations, potentially linking MCSZ with cancer development." (PMID 39395804, 2024). "Polynucleotide kinase/phosphatase (PNKP) is an important repair enzyme regulating DNA replication and repair, and its irregular expression may lead to diseases such as cancer." (PMID 35682737, 2022). "Moreover, the downregulation of PNKP by siRNA or its inhibition by small molecule inhibitors have been shown to sensitize cancer cells to IR and to topoisomerase I inhibitors." (PMID 35004293, 2021). "Mutations that reduce PNKP activity cause a devastating neurological disease but surprisingly not cancer, suggesting that other DNA repair mechanisms step into the breach in dividing PNKP-deficient cells." (PMID 28922417, 2017). "Therefore we reported the first observation in literature showing the CHO-antioxidant proteins- PNKP relationship in cancer." (PMID 26754536, 2016). "While this inhibitor has been previously reported as a potent and selective for PNKP, with an IC50 of ∼60 nM in several human cancer cell lines, our findings show it to be less effective, exhibiting an apparent IC50 of ∼20 μM in multiple TNBC cell lines." (PMID 40743845, 2025). "In the poorest cancer of the digestive system, pancreatic cancer, the lipogenic liver X receptor (LXR)–SREBP-1 axis controls polynucleotide kinase/phosphatase (PNKP) transcription for regulating cancer cell DNA repair and apoptosis." (PMID 35912181, 2022). "Currently, specific inhibitors against BER proteins such as Polβ, PNKP, FEN1, Ligase IIIα, and PARP1/PARG have been developed either to sensitize several cancers or to form synthetic lethal partnerships with common cancer mutations." (PMID 33553154, 2020). "To overcome the problem of non-specificity for cancer and, at the same time, to enhance the solubility of PNKP inhibitors for in vivo administration, we have developed NP formulations of a second generation polysubstituted imidopiperidine, named A83B4C63." (PMID 35004293, 2021). "In humans, PNKP mutations underlie the neurological disease known as MCSZ, but these individuals are not predisposed for cancer, implying effective alternative repair pathways in dividing cells." (PMID 28922417, 2017). "Inhibition of PNKP phosphatase activity in cells with concentrations of A12B4C3 and A83B4C63 in the same range of 1 to 10 μM inhibits the repair of single and double-stranded DNA breaks and sensitizes cancer cells to the topoisomerase poison camptothecin and gamma irradiation (65, –, 70)." (PMID 35412344, 2022).
neurological diseases (15 papers, 2015 to 2025). "Mutations in PNKP and resulting repair deficiency have been implicated in a variety of human neurological diseases, such as MCSZ, AOA4, etc.." (PMID 38224455, 2024). "Some PNKP genetic variants are associated with rare (less than 50 patients worldwide) autosomal recessive neurological disorders, presenting with neurodevelopmental or neurodegenerative symptoms." (PMID 35412344, 2022). "Mutations underlying the neurological disorders are primarily found within the kinase domain of PNKP, although a few have been identified in either the phosphatase or the FHA domains." (PMID 34226276, 2021). "Arguably one of the most common sources of neurological disease associated with defects in DNA strand break repair are mutations in the enzyme polynucleotide kinase-phosphatase (PNKP)." (PMID 32504494, 2020). "The importance of this activity is illustrated by existence of neurological diseases in which PNKP is mutated." (PMID 27965414, 2017). "Mutations in PNKP result in three clinically distinct neurological diseases." (PMID 32504494, 2020). "As PNKP has a vital role in both nuclear and mitochondrial DNA integrity, mutations in this enzyme or associated proteins, have several implications in the pathogenesis of neurological diseases." (PMID 31110700, 2019). "It is unclear why mutations in the same protein can result in two different neurological diseases but this may reflect the varying impact of the different mutations on PNKP function and/or the additional role of this protein in non-homologous end joining." (PMID 28821613, 2017). "Recently it has been clearly documented that deficiencies in DNA end-processing activity (such as that of PNKP, TDP1 and Aprataxin) are linked to neurological diseases." (PMID 25633985, 2015). "However, homozygous loss-of-function mutations in PNKP are associated with various neurologic diseases in human, but not with early lethality." (PMID 30875370, 2019).
tumor (6 papers, 2021 to 2025). "Consistent with the localization of mutant PNKP-GFP in the HeLa PNKP−/− cells, the patient’s tumor showed both nuclear and aberrant cytoplasmic distribution of PNKP." (PMID 35354845, 2022). "Nevertheless, a sustained inhibition of PNKP resulting from higher accumulation of its nano-formulation in tumor xenografts along with a continuous release of the drug in the tumor site might have been responsible for the higher activity of NP/A83 over CE/A83, in vivo." (PMID 35004293, 2021). "Doxorubicin alone decreased tumor growth but not significantly, while PNKP KD had a stronger effect and significantly attenuated tumor growth." (PMID 40743845, 2025).
neurodegenerative disease (5 papers, 2015 to 2025). A disorder of the central nervous system characterized by gradual and progressive loss of neural tissue and neurologic function. "Since enzymatic activity of PNKP is important for DNA repair, especially for SSB repair and NHEJ for DSB repair, genetic mutation of PNKP gene result in inherited neuronal development and neurodegenerative disease." (PMID 32970693, 2020). "Moreover, several types of variants were identified in PNKP; most are in the kinase domain, particularly in neurodegenerative diseases, as shown in this study." (PMID 35326432, 2022). "Nevertheless, most variants seem to cause reduced stability and levels of PNKP, and reduced DNA phosphatase activity in MCSZ or reduced kinase activity in neurodegenerative diseases." (PMID 35326432, 2022).
genetic disorder (4 papers, 2019 to 2025). "The vast majority of microcephalies with identified etiology result from genetic disorders, including mutations in one of the essential DNA damage repair proteins, polynucleotide kinase 3′-phosphatase (PNKP)." (PMID 35412344, 2022).
infection (1 paper, 2016). The state of being infected such as from the introduction of a foreign agent such as serum, vaccine, antigenic substance or organism. "Most importantly, FEN1 and PNKP were also highly expressed inside the gut of silkworms post infection, in contrast SWP4 was down regulated." (PMID 27708628, 2016).